IL20 (interleukin 20)
Diseases named in the same sentence as IL20 in open-access papers (continued):
Sharing a sentence is not in itself a finding about the gene and the disease.
gynecologic cancer (1 paper, 2021). "A whole range of inflammatory cytokines play also a key role in this process, such as interleukin 20 (IL-20), which was even studied on a few healthy and gynecologic cancer patients." (PMID 33802861, 2021).
heart failure (1 paper, 2021). Inability of the heart to pump blood at an adequate rate to meet tissue metabolic requirements. "We also demonstrated that IL-20 antibody injection attenuates cardiac functional impairment, including the repressed EF and FS, the increased left ventricular end-diastolic and end-systolic volumes, and downregulation of plasma markers of cardiac injury and heart failure." (PMID 33578994, 2021).
HIV-1 infection (1 paper, 2010). The type species of lentivirus and the etiologic agent of acquired immunodeficiency syndrome (AIDS). "One SNP in IL10RB (rs2266590 in intron; 4 p = 0.05) and one in IL20 (rs2981572 in 5′UTR; p = 0.006) were associated with risk of HIV-1 infection." (PMID 20976276, 2010). "Here, we hypothesize that involvement of the IL-10 molecule in HIV-1 infection and pathogenesis could be modulated through complex interactions among IL10 and its related genes, especially those (IL19, IL20 and IL24) in the flanking genomic region and the IL-10 receptor genes (IL10RA and IL10RB)." (PMID 20976276, 2010).
hyperglycaemia (1 paper, 2024). "This suggests that IL-22 signaling, and not IL-20 or IL-24 signaling, is associated with hyperglycaemia." (PMID 38811550, 2024).
hyperuricemia (1 paper, 2015). An abnormally high level of uric acid. "Seven AEs were rated as severe (SD dose-escalation phase, n = 2; MD dose-escalation phase, n = 5); all were considered unlikely to be related to treatment by the investigator except 1 non–life-threatening AE (hyperuricemia) in a patient receiving 2.0 mg/kg anti‒IL-20 in the MD dose-escalation phase." (PMID 26252485, 2015).
influenza (1 paper, 2021). An acute viral infection of the respiratory tract, occurring in isolated cases, in epidemics, or in pandemics; it is caused by serologically different strains of viruses (influenzaviruses) designated A, B, and C, has a 3-day incubation period, and usually lasts for 3 to 10 days. "Using influenza as a model, live attenuated and killed inactivated influenza vaccines stimulate many shared pathways such as signaling of many interleukins (including IL-1, IL-4, IL-6, IL-13, IL-20, and IL-27), interferon signaling, MARK1 activation, and neutrophil degranulation." (PMID 33777032, 2021).
Insulin resistance (1 paper, 2025). Increased resistance towards insulin, that is, diminished effectiveness of insulin in reducing blood glucose levels. "The potential positive impact of Tai-Chi exercise on the regulation of IL-20 is noteworthy, given that IL-20 is a multifunctional cytokine involved in inflammation and insulin resistance." (PMID 41551693, 2025).
intervertebral disc degeneration (1 paper, 2015). "The objective of this study was to detect the correlation between IL-20 and the degeneration grade of lumbar disc, analyze the influence of IL-20 on the development of intervertebral disc degeneration." (PMID 25878634, 2015). "In addition, with the advance of intervertebral disc degeneration, the content of IL-20 increase, while proteoglycan decrease gradually." (PMID 25878634, 2015).
ischemic heart disease (1 paper, 2020). "Therefore, regulation of IL-20 may contribute to cardiomyocyte apoptosis, and this might be helpful in future considerations of new therapeutic targets in the treatment of ischemic heart disease." (PMID 33456670, 2020).
leukemia (1 paper, 2023). A malignant (clonal) hematologic disorder, involving hematopoietic stem cells and characterized by the presence of primitive or atypical myeloid or lymphoid cells in the bone marrow and the blood. "In response to stimulation with IL20 in vitro, we also observed a pronounced cycling activity of CLOCK-transduced leukemia T-cells, as well as decrease of the fraction of cells at the early apoptotic stage, confirming that CLOCK-overexpressing cells are more responsive to IL20 treatment." (PMID 37620852, 2023).
lower respiratory tract infection (1 paper, 2021). "SNPs in genes coding for interleukin (IL)-8, IL-19, IL-20, IL-13 mannose-binding lectin, interferon-gamma, and a regulated on activation, normal T cell expressed and secreted polymorphism have been associated with subsequent wheeze after RSV lower respiratory tract infection in term-born infants." (PMID 34386467, 2021).
lumbar disc degeneration (1 paper, 2015). "Subsequently, we assumed IL-20 may aggravate the degeneration of lumbar disc by affecting the synthesis of proteoglycan, and the advance of lumbar disc degeneration may result in the increased expression of IL-20." (PMID 25878634, 2015).
lung carcinoma (1 paper, 2025). "The abundance of bacterial populations in the stool of lung cancer patients significantly increased the levels of IL-20, IL-24, CCL-8, and TGF-α in LUAD and LUSC patients, indicating the role of these proteins in bridging the association between gut ecology and lung cancer." (PMID 41376623, 2025).
malaria (1 paper, 2025). Malaria is a serious and sometimes fatal disease caused by a parasite that commonly infects a certain type of mosquito which feeds on humans. "FCGR2B protein demonstrated moderate discriminatory ability (AUC = 0.717), suggesting a notable but less pronounced association with malaria status compared to IL-20." (PMID 40697816, 2025). "IL-20 protein exhibited the highest discriminatory power (AUC = 0.815), indicating a strong association with malaria status." (PMID 40697816, 2025). "In the context of pregnancy-associated malaria, IL-20 may modulate the inflammatory response and placental immune tolerance, potentially impacting the severity and outcomes of the infection." (PMID 40697816, 2025). "Although NRTN expression levels may still have some association with malaria status, the association is less pronounced compared to IL-20, FCGR2B, and HO-1." (PMID 40697816, 2025). "We observed that FCGR2B, HO-1, NRTN and IL-20 were differentially expressed in plasma from malaria-infected pregnant women vs. from non-malaria-infected controls." (PMID 40697816, 2025). "This suggests that IL-20 expression levels serve as a promising biomarker for malaria diagnosis or prognosis." (PMID 40697816, 2025). "Similarly, HO-1 protein also displayed moderate discriminatory power (AUC = 0.729), indicating some association with malaria status, although not as strong as IL-20." (PMID 40697816, 2025). "Using proximity extension assay (PEA), we identified elevated IgG Fc receptor IIb (FCGR2B) and heme oxygenase-1 (HO-1) in malaria-positive pregnancies, while neurturin (NRTN) and IL-20 were downregulated." (PMID 40697816, 2025).
metabolic syndrome (1 paper, 2015). A cluster of metabolic risk factors for CARDIOVASCULAR DISEASES and TYPE 2 DIABETES MELLITUS. "Because IL-22R1 can combine not only with IL-10R2 to act as a functional IL-22R complex but can also interact with IL-20R2 to form a receptor for IL-20 and IL-24, it is likely that IL-22R1 ligands other than IL-22 may play a role in ameliorating HFD-induced metabolic syndrome." (PMID 26064446, 2015).
myasthenia gravis (1 paper, 2021). Myasthenia gravis (MG) is a rare, clinically heterogeneous, autoimmune disorder of the neuromuscular junction characterized by fatigable weakness of voluntary muscles. "On the other hand, IL-20 promotes VEGF-mediated angiogenesis including other neuroinflammatory and autoimmune pathology: e.g., myasthenia gravis (MG)." (PMID 34557075, 2021).
myocardial infarction (1 paper, 2021). Gross necrosis of the myocardium, as a result of interruption of the blood supply to the area, as in coronary thrombosis. "Next, to evaluate the therapeutic effect of IL-20 antibody in myocardial infarction, we used echocardiography to monitor cardiac function." (PMID 33578994, 2021). "We previously demonstrated that IL-20 plays a key role in modulation of cardiac damage following myocardial infarction." (PMID 33578994, 2021).
myocardial ischemia (1 paper, 2021). A disorder of cardiac function caused by insufficient blood flow to the muscle tissue of the heart. "Thus, the administration of IL-20 antibody in myocardial reperfusion, either by thrombolytic medication or using percutaneous coronary intervention, to repress myocardial ischemia-reperfusion injury could be a promising novel strategy for the improvement of AMI treatment." (PMID 33578994, 2021).
nephropathies (1 paper, 2022). "It is also important to note that the variability of the IL-20 levels may be related to the severity of kidney damage in CKD patients, but this thesis requires further analysis." (PMID 35054831, 2022). "The most frequently mentioned in scientific studies on nephropathy was IL-10, occurring, inter alia, in DN, FSMGS, MN, AKI and IL-20 found in CKD and AKI." (PMID 35054831, 2022).
non-small cell lung carcinoma (1 paper, 2021). A group of at least three distinct histological types of lung cancer, including non-small cell squamous cell carcinoma, adenocarcinoma, and large cell carcinoma. "However, dysregulation of IL-20 in non-small cell lung cancer (NSCLC) exerts anti-angiogenic effects by down-regulation of COX-2." (PMID 34557075, 2021).
oral candidiasis (1 paper, 2022). Infection of the mucosal lining of the mouth with the fungus Candida albicans. "More research is needed to localize and determine the dynamics of the expression IL-20 cytokines in the oral epithelium and how they impact inflammation, loss in body weight, and tissue repair in oral candidiasis." (PMID 36225230, 2022). "To gain further evidence for the role of the IL-20 signaling pathway in the protection or exacerbation of acute oral candidiasis, we assessed tongue fungal burdens in IL20RB-deficient mice in OPC." (PMID 36225230, 2022). "One understudied pathway that may be important for modulating oral candidiasis is the IL-20 cytokine signaling pathway that employs keratinocyte IL-20RB receptors as ligands for IL-19, IL-20, and IL-24." (PMID 36225230, 2022).
periodontitis (1 paper, 2025). An acute or chronic inflammatory process that affects the tissues that surround and support the teeth. "Additionally, IL-20 is associated with periodontitis, with IL-20 contributing to periodontitis through osteoclast formation and collagen degradation." (PMID 40724937, 2025).
prostate tumors (1 paper, 2015). "We investigated the effects of anti-IL–20 monoclonal antibody 7E on prostate tumor growth in vivo using SCID mouse subcutaneous and intratibial xenograft tumor models." (PMID 26440411, 2015).
psychosis (1 paper, 2023). "Furthermore, olanzapine seems to have marginal immunomodulatory effects in drug naïve patients in the first episode of psychosis, regulating the expression of genes related to the immune system, such as IL-17A and IL-20." (PMID 37206523, 2023).
pulmonary TB (1 paper, 2023). "While the role of IL-20 cytokines in TB is poorly investigated, one report demonstrated that IL-19 and IL-24 are elevated in pulmonary TB patients and in vitro neutralization of these cytokines resulted in an enhanced CD4+ Th1/Th17 responses." (PMID 38162636, 2023).
Sciatica (1 paper, 2024). Pain in the lower back and hip radiating in the distribution of the sciatic nerve. "Conversely, there is a negative correlation between sciatica and Interleukin-1-alpha levels (p = 0.029, OR = 1.67E−05, 95% CI =8.79E−10–0.318), Interleukin-20 levels (p = 0.007, OR = 1.59E−06, 95% CI =8.95E−11–0.028), and Interleukin-33 levels (p = 0.029, OR = 7.62E−06, 95% CI =1.86E−10–0.312)." (PMID 39015317, 2024).
Sjögren’s syndrome (1 paper, 2022). "Whether IL-20 mediates the pathogenic role in Sjögren’s syndrome-associated DED is worthy of further investigation." (PMID 35681232, 2022).
squamous cell carcinoma (1 paper, 2018). A carcinoma arising from squamous epithelial cells. "Squamous cell carcinoma and adenocarcinoma can develop in the esophagus, but the contribution of IL-20 cytokine family members to the carcinogenesis is mainly unexplored so far." (PMID 29967613, 2018).
thymoma (1 paper, 2016). A neoplasm arising from the epithelial cells of the thymus. "In clinical subtype analyses, APRIL and IL-20 were increased in patients with late-onset MG and IL-28A levels were increased in patients with thymoma-associated MG compared with healthy controls (p < 0.01)." (PMID 27172995, 2016).
tuberculosis (1 paper, 2013). A chronic, recurrent infection caused by the bacterium Mycobacterium tuberculosis. "At 24 hours, several of the cytokines (IL-10, IL-20, and IL-26) had significantly higher transcript levels in the stimulated tuberculosis-IRIS cultures (P < .001, P = .022, and P = .004, respectively)." (PMID 23303806, 2013). "Whereas analysis of fold-induction showed significant induction of IL-19, IL-20, IL-24, and IL-26 by M. tuberculosis, the differences detected between the tuberculosis-IRIS and non-IRIS groups were neither great nor statistically significant." (PMID 23303806, 2013). "In PBMCs from both tuberculosis-IRIS and non-IRIS patients, M. tuberculosis stimulation resulted in increased transcript abundance for many of the cytokines, most prominently IL-19, IL-20, IL-24, and IL-26." (PMID 23303806, 2013).
type 2 diabetes (1 paper, 2015). "Hence, future combination therapies with anti-IL20 may provide beneficial therapeutic effects in type 2 diabetes through a reduction of inflammation." (PMID 26162095, 2015).
vitiligo (1 paper, 2024). Generalized well circumscribed patches of leukoderma that are generally distributed over symmetric body locations and is due to autoimmune destruction of melanocytes. "Remarkably, many of the increased proteins in patients achieving F-VASI50 were interleukins such as IL-20 and Th2 linked cytokines IL-5 and IL-13 for which no major role in vitiligo has previously been described." (PMID 38715599, 2024).
tumor (33 papers, 2010 to 2025). "The expression of IL-20 in BC tissue is not only associated with a higher mitotic rate but also correlated with advanced tumor stages and bone metastasis." (PMID 39941053, 2025). "Antagonizing IL-20 overexpression in the tumor microenvironment effectively reduces the close association between inflammation and cancer." (PMID 38699038, 2024). "Lastly, IL-20 (cancer-promoting), a pro-inflammatory cytokine that promotes oral tumor growth, migration and tumor-associated inflammation, is also increased in plasma of RA patients." (PMID 37681925, 2023). "In in vitro studies, they found that IL-20 caused increased tumor cell proliferation and ROS production." (PMID 38258051, 2023). "By contrast, treatment of KPC or LLC tumor-bearing mice with IL-20 blockade prevented CAC-associated WAT lipolysis and maintained the adipose fat mass and body weight." (PMID 32929072, 2020). "We found that IL-20 expression was highly associated with HCC tumor stages in our clinical specimens." (PMID 29242565, 2017). "Although IL20 is associated with tumor progression through its regulation of migration and invasion, little is known about its role in the response of tumor cells to drugs." (PMID 26540344, 2015). "7E’s inhibition of tumor growth was positively associated with the downregulated expression of IL–20 in the tumor mass." (PMID 26440411, 2015). "The epigenetic silencing of IL-20RA has been correlated with poorer disease-free survival in NSCLC, suggesting that loss of IL-20 signaling may contribute to tumor progression." (PMID 40806452, 2025). "The expression of IL-20 and its receptors is subject to epigenetic regulation, supporting the concept that epigenetic alterations can contribute to the acquisition of hallmark capabilities during tumor development." (PMID 40806452, 2025). "We explored the association of IL-20 expression with inflammatory cytokines in HCC tumor formation." (PMID 29242565, 2017). "The application of a monoclonal antibody against IL-20 (anti-IL-20 mAb) in a mouse BC model provided an unfavorable microenvironment for tumor cells to colonize and grow." (PMID 39941053, 2025). "It has been widely demonstrated that IL-20 provides an advantageous microenvironment for tumor cell growth." (PMID 40806452, 2025). "This therapy also influences the tumour microenvironment by altering cytokine production, including IL-8 and IL-20, which can modulate immune responses and impact tumour progression." (PMID 39857765, 2025). "Elevated IL-20 levels in tumor tissue correlate with poor overall survival in patients with pancreatic ductal adenocarcinoma (PDAC)." (PMID 40806452, 2025). "In describing the role of the immune system in HCC, Giuseppe made it clear that IL-1, TNF-α, and IL-6 are involved in invasion and metastasis, whereas TGF-β and IL-20 reduce the anti-tumor immune response." (PMID 38699038, 2024). "For instance, IL-20 can promote the differentiation of monocytes into pro-tumorigenic TAMs, which can further secrete cytokines and growth factors that support tumor growth and metastasis." (PMID 39450166, 2024). "For example, monocytes can secrete IL-20 in response to various stimuli, including the presence of tumor cells or other inflammatory signals." (PMID 39450166, 2024). "This indicates that IL-20 released by inflammation at the early stages of tumor development promotes mutagenesis of cancer cells and accelerates their transformation to a highly malignant state." (PMID 38699038, 2024). "Interleukin 20 (IL-20) is a cytokine assigned to the interleukin 10 family described as tumor promoting." (PMID 38033043, 2023). "The authors observed that inhibition of IL-20 was able to reduce tumor size, attenuate CAC symptoms, and decrease tumor PD-L1 expression." (PMID 36033972, 2022). "IL-20 is a tumor-promoting cytokine partly due to their capacity to induce proliferation and migration of tumor cells." (PMID 34745140, 2021).